SHROOM3 (shroom family member 3)
Description:
Controls cell shape changes in the neuroepithelium during neural tube closure. Induces apical constriction in epithelial cells by promoting the apical accumulation of F-actin and myosin II, and probably by bundling stress fibers (By similarity). Induces apicobasal cell elongation by redistributing gamma-tubulin and directing the assembly of robust apicobasal microtubule arrays (By similarity).
Synonyms: KIAA1481; SHRML; MSTP013; SHRM; APXL3
Tractability: Antibody: UniProt places it where antibodies can reach, with medium confidence; its Gene Ontology location is reachable by antibodies, with medium confidence. PROTAC: its protein half-life has been measured.
Gene: Protein-coding gene on chromosome 4 (76,435,229 to 76,783,253, forward strand). Ensembl gene ENSG00000138771.
Subcellular location: Cell junction, adherens junction; Cytoplasm, cytoskeleton; Apical cell membrane
Gene Ontology:
Molecular function: protein binding; actin filament binding
Biological process: actin filament organization; apical protein localization; cell morphogenesis; cellular pigment accumulation; pattern specification process
Cellular component: adherens junction; apical junction complex; apical plasma membrane; cortical actin cytoskeleton; cytoskeleton
Genetic constraint (gnomAD): Loss-of-function variants: 47 observed, 133.7 expected, observed/expected ratio (o/e) 0.35, 90% interval 0.28 to 0.45. The upper end of that interval is the gene's LOEUF score, 0.45, which puts it in group 1 of 6, group 1 being the genes least tolerant of losing a copy. Missense variants: 2,491 observed, 2,613.5 expected, observed/expected ratio (o/e) 0.95, 90% interval 0.92 to 0.99. Synonymous variants: 1,062 observed, 1,065.1 expected, observed/expected ratio (o/e) 1, 90% interval 0.95 to 1.05.
Homologues: Orthologues: chimpanzee SHROOM3 (96% identical), macaque SHROOM3 (96% identical), mouse Shroom3 (71% identical), rat Shroom3 (70% identical), dog SHROOM3 (70% identical), guinea pig SHROOM3 (63% identical), tropical clawed frog shroom3 (33% identical), zebrafish shroom3 (27% identical), Drosophila melanogaster Shrm (15% identical). Paralogues in human: SHROOM2 (25% identical), SHROOM4 (18% identical), SHROOM1 (12% identical).
Diseases named in the same sentence as SHROOM3 in open-access papers:
SHROOM3 is named in the same sentence as 50 diseases in open-access papers, as found by Europe PMC text mining. Sharing a sentence is not in itself a finding about the gene and the disease. The quoted sentences say what the papers report.
chronic kidney disease (14 papers, 2014 to 2025). Impairment of the renal function secondary to chronic kidney damage persisting for three or more months. "SHROOM3 encodes an actin-binding protein involved in kidney development and has been associated with chronic kidney disease through genome-wide association studies." (PMID 40558522, 2025). "Multiple large-scale genome-wide association meta-analyses studies have reliably identified an association between genetic variants within the SHROOM3 gene and chronic kidney disease." (PMID 38107159, 2023). "Genome-wide association studies have identified genetic variants near the transcription start site of the SHROOM3 gene associated with chronic kidney disease." (PMID 38107159, 2023). "CUBN, UMOD, and SHROOM3 were identified by human GWAS as being associated with albuminuria, kidney function, and chronic kidney disease (CKD)." (PMID 26219736, 2015). "Furthermore, research has shown that genetic variations within SHROOM3 are associated with chronic kidney disease." (PMID 40416952, 2025). "Furthermore, a previous study reported that SHROOM3 was associated with chronic kidney disease with high levels of oxidatively damaged DNA and genomic instability." (PMID 35459784, 2022). "Shroom3 is an actin-associated regulator of cell morphology that is required for neural tube closure, formation of the lens placode, and gut morphogenesis in mice and has been linked to chronic kidney disease and directional heart looping in humans." (PMID 25171888, 2014). "Several genome-wide association studies (GWAS) have identified genetic variances primarily in the 5’ region of SHROOM3, associated with chronic kidney disease (CKD) and poor transplant outcomes." (PMID 37313360, 2023). "Furthermore, intronic SHROOM3 genetic variants in multiple GWAS have been associated with chronic kidney disease (CKD) and kidney function markers: eGFR and creatinine levels." (PMID 38279093, 2024). "SHROOM3 and SERPINF1 play a role in kidney transplantation and chronic kidney disease, while RCN3 and NTM are potential prognostic molecules for non‐small cell lung cancer and ovarian cancer, but they have not been explored in kidney tumors." (PMID 37676078, 2023). "Using podocyte-specific SHROOM3 knockout mice and an Adriamycin (ADR)-induced nephropathy mouse model, we demonstrated that glomerular SHROOM3, specifically in podocytes, was upregulated following ADR treatment during the acute injury phase but downregulated in chronic kidney disease." (PMID 40558522, 2025).
acute kidney injury (4 papers, 2023 to 2025). Sudden and sustained deterioration of the kidney function characterized by decreased glomerular filtration rate, increased serum creatinine or oliguria. "Serum Mg2+ levels were associated with MUC1/TRIM46 (p = 2.9 × 10−7), SHROOM3 (p = 4.0 × 10−7), and SLC22A7 (p = 1.0 × 10−6) at nominal significance, which is in combination with the eQTL data suggesting that they are possible candidates for renal failure." (PMID 38279093, 2024). "Yet, there is a possibility that individuals with Shroom3 genetic anomalies may experience worsened kidney disease when in the presence of an external insult, such as acute kidney injury, an area that requires further exploration in future studies." (PMID 37313360, 2023). "Evidence that reduced Shroom3 expression could contribute to kidney disease postnatally was gathered when 3-month-old Shroom3 heterozygous null mice were exposed to an acute kidney injury." (PMID 38107159, 2023).
Hypertension (4 papers, 2021 to 2024). The presence of chronic increased pressure in the systemic arterial system. "The significant expression of SHROOM3 on locus 4q21.1 in relation to AFLD-Hypertension (P = 3.26E-08, PP.H4 = 0.956) and AFLD-CAD (P = 2.65E-09, PP.H4 = 0.968) should be noted." (PMID 38523778, 2024). "Although several genes, including uromodulin (UMOD), shroom family member 3 (SHROOM3) and engulfment and cell motility 1 gene (ELMO1) have been strongly associated with CKD, their roles in hypertension and CV outcome are still unclear." (PMID 36360378, 2022).
kidney damage (4 papers, 2011 to 2025). "Collectively, these findings demonstrate that podocyte-specific deletion of Shroom3 exacerbates ADR-induced nephropathy, highlighting its protective role against podocyte injury." (PMID 40558522, 2025). "To investigate the potential role of SHROOM3 in nephropathy, we initially assessed its distribution across kidney cell types using the Kidney Interactive Transcriptomics (KIT) database." (PMID 40558522, 2025). "Variants in CASZ1 and SHROOM3 were common for microalbuminuria and UACR, and DPEP1 along with COL4A3 were common for kidney damage and UACR (p < 0.001)." (PMID 37446387, 2023). "Variants in CASZ1 and SHROOM3 were associated with microalbuminuria and UACR, and DPEP1 along with COL4A3 were common for kidney damage and UACR." (PMID 37446387, 2023). "Examination of the top 100 SNP interactions with c22 risk variants identified SNPs within two previously reported nephropathy susceptibility genes, FRMD3 and SHROOM3." (PMID 21698141, 2011). "In conclusion, the heterozygous loss of Shroom3 in mice does not result in overt kidney damage or decreased kidney function." (PMID 37313360, 2023). "To understand how SHROOM3 responds during kidney injury, we analyzed a single-cell RNA sequencing (scRNA-seq) dataset from mice with ADR-induced nephropathy." (PMID 40558522, 2025). "To further explore how Shroom3 expression changes during progressive glomerular damage, we employed the ADR-induced nephropathy mouse model, a well-established experimental system that recapitulates podocyte injury and proteinuria." (PMID 40558522, 2025). "Using podocyte-specific Shroom3 knockout mice and transcriptomic approaches, we assessed SHROOM3 function in vivo and in vitro, focusing on Adriamycin (ADR)-induced nephropathy, a validated FSGS model characterized by progressive podocyte loss and glomerulosclerosis." (PMID 40558522, 2025). "CUBN-rs1801239 and DDR1-rs116772905 were associated with all the UACR-derived phenotypes, (along with SHROOM3-rs17319721 and ALLC-rs12615970, except for macroalbuminuria) at least in the overall and non-diabetic cohorts, but not with kidney damage." (PMID 37446387, 2023).
anencephaly (3 papers, 2019 to 2021). A rare neural tube defect during pregnancy, resulting in the absence of a large portion of the brain and skull in the fetus. "This study identified one LoF DNV in SHROOM3 gene, which was assumed to be associated with the development of anencephaly." (PMID 31849593, 2019).
focal segmental glomerulosclerosis (3 papers, 2021 to 2025). A renal disorder characterized by sclerotic lesions in the glomeruli. "Clinically, the glomerular SHROOM3 expression positively correlated with glomerular filtration rates in focal segmental glomerulosclerosis patients." (PMID 40558522, 2025). "SHROOM3 also appears to protect the glomerular structure and function in conditions such as focal segmental glomerulosclerosis." (PMID 38107159, 2023). "While emerging evidence points to a protective function in focal segmental glomerulosclerosis (FSGS), the mechanistic basis of SHROOM3 in podocyte pathophysiology remains unclear." (PMID 40558522, 2025). "Herein, we report that Shroom3 knockdown, via Fyn inhibition, induced albuminuria with foot process effacement (FPE) without focal segmental glomerulosclerosis (FSGS) or podocytopenia." (PMID 34473647, 2021).
glomerulosclerosis (3 papers, 2015 to 2025). A hardening of the kidney glomerulus caused by scarring of the blood vessels. "Initially identified in neural tube defects, where its deficiency causes embryonic lethality via exencephaly in mouse models, SHROOM3 was later implicated in renal pathology when heterozygous null mice developed glomerulosclerosis and foot process effacement by one year of age." (PMID 40558522, 2025). "Given the established involvement of SHROOM3 in glomerulosclerosis and the podocytopathies, we comprehensively investigated its role in podocytes under both physiological and pathological conditions." (PMID 40558522, 2025). "The analysis of 1-year-old Shroom3 heterozygous null mice exhibit glomerulosclerosis and smaller podocytes with foot process flattening and effacement." (PMID 38107159, 2023). "A defect in the actin-binding domain of SHROOM3 results in impairment of the glomerular filtration barrier leading to albuminuria and glomerulosclerosis." (PMID 26219736, 2015). "Podocyte-specific Shroom3 knockout (Shroom3-PKO) mice exhibited exacerbated ADR-induced proteinuria and accelerated glomerulosclerosis progression." (PMID 40558522, 2025). "Genetic ablation of SHROOM3 in podocytes exacerbated ADR-induced proteinuria, diminished podocyte markers (nephrin, podocin, and WT1), and accelerated glomerulosclerosis." (PMID 40558522, 2025).
spina bifida (3 papers, 2010 to 2015). A congenital neural tube defect in which vertebrae are not fully formed. "In mice it has been shown that mutations in the SHROOM3 gene result in exencephaly, acrania, facial clefting, and spina bifida; all presumably due to failed closure of the neural tube." (PMID 20187927, 2010). "Only knockouts of the cytoskeleton-associated proteins Shroom3 and MARCKS-related protein yield both exencephaly and spina bifida and, even here, the frequency of exencephaly exceeds spina bifida." (PMID 26040287, 2015). "Shroom3+/gt;Vangl2+/Lp embryos develop spina bifida with a penetrance of 37.5% (9 out of 24)." (PMID 25596276, 2015).
nephrotic syndrome (2 papers, 2020 to 2025). A collection of symptoms that include severe edema, proteinuria, and hypoalbuminemia; it is indicative of renal dysfunction. "In a cohort of patients with nephrotic syndrome, glomerular SHROOM3 expression was markedly lower in patients with eGFR < 60 mL/min/1.73 m2 compared to those with eGFR ≥ 60 mL/min/1.73 m2 and significantly correlated with eGFR levels." (PMID 40558522, 2025).
Stroke (2 papers, 2020 to 2023). Sudden impairment of blood flow to a part of the brain due to occlusion or rupture of an artery to the brain. "Specifically, Shroom3 is involved in the Shroom3-Rho kinase signaling complex and is shown to inhibit axonal outgrowth and stroke recovery; MuSK gene encodes for MuSK tyrosine kinase, which is crucial for NMJ maintenance." (PMID 32629989, 2020). "A recent RNAseq study of the TA muscle using a mouse stroke model in 5 m mice found altered transcriptomes compared to age-matched non-stroke mice including: an upregulation in stroke mice >log2fc1 of Gadd45a, Shroom3, Chrna2, and MuSK, along with downregulation (log2fc < −1) of P2ry1." (PMID 37876943, 2023). "Sspo, Shroom3, MuSK, Chrna2, Sorbs2, and Coro6 were upregulated in response to stroke." (PMID 32629989, 2020).
Type 2 diabetes (2 papers, 2013 to 2024). "Our results suggest that genetic variation in or near TAF3, MUC1/TRIM46, SHROOM3, and SLC22A7 are associated with the regulation of serum Mg2+ concentrations which may be partially explained by renal function, in type 2 diabetes." (PMID 38279093, 2024). "In conclusion, serum magnesium concentrations are associated with genetic variability around the regions of TAF3, MUC1/TRIM46, SHROOM3, and SLC22A7 in type 2 diabetes." (PMID 38279093, 2024).
acute lymphoblastic leukaemia (1 paper, 2022). "Mutations in SHROOM3 have also been observed in relapsed acute lymphoblastic leukaemia." (PMID 36037157, 2022).
atherosclerosis (1 paper, 2017). A disease characterized by the build-up of fatty material and calcium deposition in the arterial wall resulting in partial or complete occlusion of the arterial lumen. "In a study that first reported on the kidney function of a general population, CX3CR1 rs3732379 SNP was associated with atherosclerosis of the coronary artery, SHROOM3 rs17319721 and PIP5K1B rs4744712 were associated with kidney disease." (PMID 29016630, 2017).
chronic allograft nephropathy (1 paper, 2023). "In a study of 540 3-month post-transplant kidney biopsies, for each rs17319721 risk allele in the donor kidney, there were greater SHROOM3 mRNA expression (P < .05) and increased risk of chronic allograft nephropathy in the transplant recipients (odds ratio = 1.98, confidence interval = 1.10-3.59)." (PMID 38107159, 2023). "The association with chronic allograft nephropathy is thought to be due to the rs17319721 variant generating a T-cell factor/lymphoid enhancer factor (TCF/LEF) transcription factor binding site in the intronic region between exons 1 and 2 of the SHROOM3 gene." (PMID 38107159, 2023).
clear cell renal cell carcinoma (1 paper, 2025). "In addition, bioinformatics analysis revealed that SHROOM3 is a strong predictor of prognosis, immune activity, and treatment response of clear cell renal cell carcinoma." (PMID 40173324, 2025).
coloboma (1 paper, 2025). An abnormality in which a part of a structure in one or both eyes is missing. "This phenotype is Rho-kinase dependent as mice with a homozygous missense mutation in the domain of Shroom3 that associates with Rho-kinase also have colobomas where the optic margins fail to approach each other." (PMID 40113025, 2025). "In order to determine how Shroom3 deficiency leads to a coloboma a conditional knock out allele of Shroom3 was generated to permit a tissue specific approach." (PMID 40113025, 2025). "Together, the findings presented here enhance our understanding of Shroom3’s role in optic fissure closure and its essential contribution to preventing coloboma formation." (PMID 40113025, 2025). "In both whole embryo and retinal specific Shroom3 knockout embryos, a novel type of coloboma was observed consisting of the formation of an ectopic infolding of the fused ventral NR." (PMID 40113025, 2025). "Two distinct phenotypes that lead to colobomas are observed in Shroom3 mutants." (PMID 40113025, 2025). "These distinct model epithelia closely match the geometry of control and severely affected Shroom3 mutant embryos with a coloboma and suggest that the change in RPE geometry contributes to the inability of the optic margins to align themselves during morphogenesis." (PMID 40113025, 2025). "The results described herein provide further mechanistic insight into two distinct steps of optic fissure closure that are Shroom3 dependent and necessary to prevent coloboma formation: the approach of the optic fissure margins and the reestablishment of apical-basal polarity." (PMID 40113025, 2025).
colorectal cancer (1 paper, 2022). A primary or metastatic malignant neoplasm that affects the colon or rectum. "There are few reports available on aminopeptidase-like 1 (NPEPL1) and shroom family member 3 (SHROOM3); however, Shen and colleagues found that NPEPL1 can act as an oncogene in colorectal cancer." (PMID 36330441, 2022).
craniofacial microsomia (1 paper, 2022). "There is no established relation between SHROOM3 and NBL, but SHROOM3 has been identified as a strong candidate involved in the pathogenesis of craniofacial microsomia, which is a disease believed to be partially caused by disturbances of neural crest cells during embryogenesis." (PMID 36037157, 2022).
dilated cardiomyopathy (1 paper, 2024). Cardiomyopathy which is characterized by dilation and contractile dysfunction of the left and right ventricles. "In cardiomyocytes, distinct genes such as TMTC1, ART3, ARHGAP24, SHROOM3, and XIST were linked to dilated cardiomyopathy, Neo-Hypoplastic Left Heart Syndrome, hypertrophic cardiomyopathy, HF-Hypoplastic Left Heart Syndrome, and Tetralogy of Fallot, respectively." (PMID 39202774, 2024).
frontal encephalocele (1 paper, 2020). "In 5 cases of frontal encephalocele and occipital cervical spina bifida aperta, we observed 3 PDRVs in the cytoskeleton genes SHROOM2, SHROOM3, and VCL encoding VINCULLIN (P = 0.040)." (PMID 32650820, 2020).
glomerular disease (1 paper, 2023). "Taken together, the abnormal molecular phenotype seen with reduced Shroom3 expression at 3 months may contribute to increased sensitivity to kidney disease and worsened tubular repair and glomerular disease after a kidney insult or with aging." (PMID 37313360, 2023).
heart failure (1 paper, 2025). Inability of the heart to pump blood at an adequate rate to meet tissue metabolic requirements. "This presents the possibility that under conditions of heart failure or ischemic damage, Shroom3 may be upregulated in the adult heart in a compensatory manner." (PMID 40920782, 2025).
hypogonadism (1 paper, 2025). A disorder characterized by decreased function of the gonads. "NYNRIN, TUFM, and SH2B1 were uniquely identified by colocalization analysis of hypogonadism, while NF1, PABPC4, and SHROOM3 were uniquely identified through colocalization analysis of total testosterone." (PMID 40316537, 2025).
liver disease (1 paper, 2024). "While SHROOM3 has been implicated in various studies for its association with cardiovascular disease, its involvement in liver disease remains unreported." (PMID 38523778, 2024).
neuroblastoma (1 paper, 2025). Neuroblastoma (NB) is the most common solid, extracranial childhood tumor. "SHROOM3 is crucial for regulating cytoskeletal proteins and has been identified as a novel coding variant in high-risk neuroblastoma." (PMID 40308607, 2025).
renal fibrosis (1 paper, 2025). A final common manifestation of a wide variety of chronic kidney diseases characterized by glomerulosclerosis and tubulointerstitial fibrosis. "Enhancer variants in Shroom3 associate with renal fibrosis (TIF), but with reduced albuminuria." (PMID 41469391, 2025).